DDX3X (DEAD-box helicase 3 X-linked)
Diseases named in the same sentence as DDX3X in open-access papers (continued):
Sharing a sentence is not in itself a finding about the gene and the disease.
cervical cancer (6 papers, 2015 to 2022). A primary or metastatic malignant neoplasm involving the cervix. "DDX3X is expressed in many human malignancies, including cancers of the breast, lung, colon, liver, gallbladder, cervical cancer, and brain." (PMID 26184164, 2015). "A special case is represented by the transcription factor YY1, which was found to interact with both DDX3X and DDX5 in cervical cancer, where it can act both as an oncosuppressor and an oncogene, depending on the subset of genes that are activated." (PMID 35954483, 2022). "Thus, it would be worth investigating whether this mechanism plays a role in modulating the functions of DDX3X and YY1 in cervical cancer." (PMID 35954483, 2022).
epilepsy (6 papers, 2020 to 2025). A brain disorder characterized by episodes of abnormally increased neuronal discharge resulting in transient episodes of sensory or motor neurological dysfunction, or psychic dysfunction. "Studies have established clear associations between DDX3X mutations and a spectrum of neurological conditions, including epilepsy, autism spectrum disorder (ASD), and intellectual disability, alongside links to immune dysregulation and oncogenesis." (PMID 41393511, 2025). "Differently, a hundred patients are reported in literature mutated in DDX3X with various clinical features including hypotonia, movement disorder, behavioural problems, corpus callosum hypoplasia and epilepsy." (PMID 34356170, 2021).
head and neck squamous cell carcinoma (6 papers, 2015 to 2025). A squamous cell carcinoma that arises from any of the following anatomic sites: lip and oral cavity, nasal cavity, paranasal sinuses, pharynx, larynx, and salivary glands. "Instead, in head and neck squamous cell carcinoma (HNSCC), the oncogenic action of DDX3X was recently described." (PMID 35954483, 2022). "In head and neck squamous cell carcinoma (HNSCC), DDX3X cooperates with the CBC-eIF3 complex to enhance some uORF-containing mRNAs." (PMID 33627125, 2021).
infertile (6 papers, 2019 to 2025). "Conversely, the loss of DDX3Y confers infertility in human males, despite the robust expression of DDX3X in germ-line tissues." (PMID 34535544, 2021). "First, we quantified DDX3X transcripts in LCLs from azoospermic (infertile) males with AZFa micro-deletions." (PMID 39026797, 2024). "MiR-424 was then detected in the seminal plasma of infertile patients with high DFI(DNA Fragmentation Index); this miRNA was down-regulated but Ddx3x was upregulated in the infertile group." (PMID 31382975, 2019). "Interestingly, Che and collaborators reported that Ddx3x gene and its protein are expressed in human SP, but they resulted upregulated in the infertile group, where the miR-424 was down-regulated." (PMID 33022946, 2020). "MiR-424 downregulation in infertile men may induce spermatogenic cell apoptosis and sperm DNA damage by directly acting on the target gene locus Ddx3x, resulting in male infertility." (PMID 31382975, 2019). "The absence of DDX3X protein in premeiotic spermatids could explain its inability to rescue the infertility phenotype conferred by DDX3Y loss." (PMID 34535544, 2021). "The identification of infertile men with LoF variants in DDX3Y, therefore, further supports the assumption that activity of DDX3Y can also not be rescued in vivo by DDX3X, which is again a result of the celltype-specific expression profile of both proteins in testicular tissue." (PMID 36997603, 2023).
lung adenocarcinoma (6 papers, 2014 to 2025). A carcinoma that arises from the lung and is characterized by the presence of malignant glandular epithelial cells. "Notably, elevated DDX3X expression was associated with poorer overall survival and progression-free intervals in lung adenocarcinoma (LUAD)." (PMID 40885716, 2025). "To confirm that this phenomenon was not limited to PC9 cell line, we transfected HCC4006, a human lung adenocarcinoma harboring an EGFR exon 19 deletion, with cDNA encoding DDX3X (HCC4006 S1, HCC4006 S2)." (PMID 25343452, 2014). "However, it is unique finding that untreated lung adenocarcinoma cells contained a subpopulation strongly expressing DDX3X and accompanied by signal switching, CSC-like phenotypes, and evidence of the EMT." (PMID 25343452, 2014). "To elucidate whether DDX3X expression was correlated with CSC-like properties, we transfected PC9 cells, lung adenocarcinoma cells harboring an EGFR exon 19 deletion mutation, with cDNA encoding DDX3X and established a novel cell line, termed A-1 cells, which overexpressed DDX3X." (PMID 25343452, 2014). "The results showed that the mRNA expression levels of ESR1, DDX3X, MAPK10, KIT, FOXO1, and MCL1 were significantly lower in both lung adenocarcinoma (LUAD) and lung squamous cell carcinoma (LUSC) tissues (p < 0.001) than normal lung tissues." (PMID 38180107, 2023).
lymph node metastasis (6 papers, 2015 to 2024). "A clinical study further illustrated the correlation of high pathological stage, lymph node metastasis and unfavored prognosis in gallbladder cancer patients displaying high DDX3X levels." (PMID 32326089, 2020). "Additionally, low DDX3X levels have been showed to be correlated with inferior overall survival in patients with RCC, and this phenotype is also correlated with tumor size, lymph node metastasis, and distant metastasis." (PMID 38316768, 2024).
microcephaly (6 papers, 2020 to 2025). A congenital or acquired developmental disorder in which the circumference of the head is smaller than normal for the person's age and sex. "Here, we report Ser584 O-GlcNAcylation of the RNA helicase DDX3X, a microcephaly associated protein, as a proteostatic mechanism regulating S-phase entry." (PMID 40592469, 2025). "In mouse models of DDX3X ID, the microcephaly observed in female DDX3X loss-of-function mice stemmed from reduced proliferation of neuronal progenitors during embryonic corticogenesis." (PMID 40592469, 2025). "Strikingly, homozygous loss of Ddx3x from neural progenitors and their progeny led to profound microcephaly in cKO females at postnatal day 0 (P0)." (PMID 35762573, 2022). "First, we show brain development is sensitive to Ddx3x dosage; complete Ddx3x loss from neural progenitors causes microcephaly in females, whereas hemizygous males and heterozygous females show reduced neurogenesis without marked microcephaly." (PMID 35762573, 2022). "Phenotypes associated with DDX3X in the mouse ortholog include abnormal embryogenesis, microcephaly and abnormal neural tube closure." (PMID 33682875, 2021). "Defects in DDX3X function in humans is associated with brain and behavioral abnormalities, microcephaly, facial dysmorphism, hypotonia, aggression and movement disorders and/or spasticity in female and probably in male." (PMID 32012899, 2020). "DDX3X missense, frameshift and nonsense variants cause an ID syndrome that presents with autistic spectrum behaviours, delayed language acquisition, eye malformation and microcephaly." (PMID 40592469, 2025). "Cortex-specific Ddx3x LoF in female mice causes extensive apoptosis and microcephaly." (PMID 41312597, 2025). "Complete loss of Ddx3x in a conditional knockout (Ddx3x-cKO) mouse model led to microcephaly only in females, which might suggest that expression of the Y-linked homolog Ddx3y explains why Ddx3x-cKO male mice are phenotypically milder than Ddx3x-cKO females." (PMID 36293143, 2022). "Conditional knockout of Ddx3x in neural progenitors using Emx1-Cre leads to microcephaly in female mice." (PMID 35762573, 2022). "With a recently reported mouse model of a catalytically deficient OGT-CDG variant, future work investigating the possible mechanistic link between DDX3X O-GlcNAcylation and microcephaly may yield insights into the aetiology of this poorly understood disease." (PMID 40592469, 2025). "Thus, compared to Ddx3x haploinsufficiency, Ddx3xT532M cHet female mice have a very mild microcephaly, whereas Ddx3xT532M cHemi males have a profound microcephaly." (PMID 41312597, 2025). "Our results here suggest that hypo-O-GlcNAcylation of DDX3X could be a candidate conveyor of the microcephaly observed in OGT-CDG patients." (PMID 40592469, 2025). "Complete loss of Ddx3x led to microcephaly in females, but not in hemizygous males, suggesting that brain development is sexually dimorphic." (PMID 35762573, 2022). "A previous bioinformatic study of the O-GlcNAcome highlighted the presence of two O-GlcNAc sites—Ser584 and Ser588—in the DDX3X C-terminal extension (CTE), deletions of which resulted in microcephaly in patients." (PMID 40592469, 2025).
osteosarcoma (6 papers, 2017 to 2024). A usually aggressive malignant bone-forming mesenchymal neoplasm, predominantly affecting adolescents and young adults. "For example, the knockdown of DDX3X did not yield a significant impact on SG assembly, whereas pharmacological inhibition of DDX3X restricted SG formation in human osteosarcoma U2OS cells." (PMID 38539466, 2024). "It has been reported that the interaction between DDX3X and hnRNPK could play a pro-apoptotic role in U2OS osteosarcoma cells under DNA-damage conditions." (PMID 37149668, 2023). "Moreover, the interaction between DDX3X and hnRNPK could play a pro-apoptotic role in U2OS osteosarcoma cells under DNA-damage conditions." (PMID 37149668, 2023).
amyotrophic lateral sclerosis (5 papers, 2019 to 2023). Amyotrophic lateral sclerosis (ALS) is a neurodegenerative disease characterized by progressive muscular paralysis reflecting degeneration of motor neurons in the primary motor cortex, corticospinal tracts, brainstem and spinal cord. "Their study investigated effects of DDX3X on translation initiation from expanded hexanucleotide GGGGCC repeats in C9ORF72 that are a cause of Amyotrophic Lateral Sclerosis (ALS) and frontotemporal dementia." (PMID 36393867, 2022). "Moreover, another study has revealed that the interplay between CK1ε and DDX3X has also a role in the insurgence of neurodegenerative diseases, as in amyotrophic lateral sclerosis (ALS)." (PMID 32899434, 2020).
autism spectrum disorder (4 papers, 2021 to 2025). A spectrum of developmental disorders that includes autism, and Asperger syndrome. "DDX3X mutations are associated with neurodevelopmental disorders, including DDX3X syndrome and autism spectrum disorder." (PMID 39836689, 2025). "Mutations in the RNA binding protein DDX3X cause diverse neurodevelopmental pathologies including autism spectrum disorder (ASD) and intellectual disability." (PMID 39836689, 2025). "De novo mutations in the RNA binding protein DDX3X cause neurodevelopmental disorders including DDX3X syndrome and autism spectrum disorder." (PMID 39836689, 2025). "Based on diagnostic clinical assessments, 80% of individuals with DDX3X variants met diagnostic criteria for ID, 60% for autism spectrum disorder, and 53% for attention deficit / hyperactivity disorder (ADHD)." (PMID 35536379, 2023). "Heterozygous inactivating mutations in DDX3X are linked to DDX3X syndrome, a neurodevelopmental delay and autism-spectrum disorder." (PMID 34535544, 2021). "The children were divided into two groups: those diagnosed with autism spectrum disorder and those with DDX3X syndrome (due to the rarity of the syndrome, children diagnosed with DDX3X mutations with and without ASD were included in this group)." (PMID 39768765, 2024).
breast tumor (4 papers, 2011 to 2025). "In primary human breast tumors, the most common ITGB1 isoform 1 A was positively correlated to Suppressor-SFs such as DDX3X and DHX9 while being negatively correlated to Enhancer-SFs such as CCDC12 and FAM50A." (PMID 30940821, 2019).
dengue (4 papers, 2017 to 2025). "We observed co-IP of capsid and DDX3X respectively demonstrating the interaction of dengue capsid and DDX3X in the context of dengue infection." (PMID 29387631, 2017). "Thus, our study identifies DDX3X as a dengue virus capsid interacting protein and indicates a potential link between the antiviral functions of DDX3X and dengue capsid at later stages of dengue infection." (PMID 29387631, 2017). "DDX3X binds dengue virus capsid and NS5 proteins, but knockdown showed differential effects on virus production.DDX3X inhibitors suppress dengue virus infection in Huh-7 and Vero cells.DDX3X is required for IFN-β release and inhibits virus replication in HEK-293 cells." (PMID 36110852, 2022).
developmental delay (4 papers, 2017 to 2025). "A de novo heterozygous missense variant in DDX3X was detected in a female patient with facial dysmorphism and developmental delay." (PMID 40558542, 2025). "Altogether, our study expanded the clinical and genetic spectrum associated with DDX3X neurodevelopmental disorder and evaluated the degree of developmental delay by a standardized scale." (PMID 35392274, 2022).
Ewing sarcoma (4 papers, 2017 to 2022). A small round cell tumor that lacks morphologic, immunohistochemical, and electron microscopic evidence of neuroectodermal differentiation. "Moreover, the inhibition of DDX3X activity by RK-33 altered the Ewing sarcoma cellular proteome, reducing malignant cell growth." (PMID 35954483, 2022).
HCMV infection (4 papers, 2015 to 2025). "It is also worth mentioning that HCMV infection enhances the expression of Grb2 and DDX3X, facilitating viral replication and spread." (PMID 40592844, 2025). "HCMV infection upregulates the expression of DDX3X, promoting virus spread and replication." (PMID 40606174, 2025).
leukemia (4 papers, 2014 to 2025). A malignant (clonal) hematologic disorder, involving hematopoietic stem cells and characterized by the presence of primitive or atypical myeloid or lymphoid cells in the bone marrow and the blood. "DDX3X mutations are implicated in the pathology of cancers (e.g., brain cancer, leukemia, and head and neck cancer) and neurodevelopmental disorders (e.g., intellectual disability and autism)." (PMID 38539466, 2024). "Overall, the protein–protein interaction analysis indicates DDX3X as a regulatory hub in leukemia, positioning it as a prospective therapeutic target." (PMID 40564907, 2025). "DDX3X was found to be involved in critical cellular pathways, including Wnt/β-catenin and MAPK signaling, both of which are frequently dysregulated in leukemia." (PMID 40564907, 2025).
renal cell carcinoma (4 papers, 2020 to 2024). "DDX3X appears to be epigenetically silenced in renal cell carcinoma and has been discussed as a potential therapeutic target." (PMID 36158701, 2022). "However, DDX3X’s role in renal cell carcinoma (RCC) progression remains largely unknown." (PMID 32326089, 2020).
triple-negative breast carcinoma (4 papers, 2023 to 2025). An invasive breast carcinoma which is negative for expression of estrogen receptor (ER), progesterone receptor (PR), and human epidermal growth factor receptor 2 (HER2). "STING-independent, DDX3X-mediated cytosolic DNA sensing and immune activation in TREX1-deficient triple negative breast cancer cells has also been reported." (PMID 40581636, 2025).
arenavirus infection (3 papers, 2018 to 2022). "However, DDX3X negatively regulates type I interferon production during arenavirus infection, and interactions between DDX3X and arenavirus nucleoprotein promote viral replication." (PMID 32033386, 2020).
chronic lymphocytic leukemia (3 papers, 2021 to 2024). "In recent years, mutations in DDX3X have been reported to be involved in chronic lymphocytic leukaemia (CLL), an incurable disease with variable clinical presentation and evolution." (PMID 33627125, 2021).
gastric cancer (3 papers, 2019 to 2025). A primary or metastatic malignant neoplasm involving the stomach. "Data from a recent study further showed the binding of DDX3X with circular RNA, circ-CTNNB1, to facilitate cancer invasion and metastasis in gastric cancer via the transactivation of YY1 and activation of downstream β-catenin signaling." (PMID 31906196, 2019).
hepatitis B (3 papers, 2019 to 2023). "It has also been shown that miR-125b is associated with hepatitis B and has been targeted with genes that include IL6, DDX3X, STAT2, STAT3, SMAD4, CDKN1B, MAP3K1 and so on from our results." (PMID 34988221, 2021). "In liver hepatocellular cells, previous findings indicated that 5-HT treatment could augment 5-HT receptor 7-mediated DDX3X promoter activity as well as the induction of an innate immunity to abolish hepatitis B virus (HBV) infection." (PMID 37371098, 2023). "Existing studies on Ddx3x mainly focus on its modulatory role in the infection of HIV and HCV and the generative mechanism of complications after hepatitis B and C infection." (PMID 31382975, 2019).
invasive breast carcinoma (3 papers, 2013 to 2019). A carcinoma that infiltrates the breast parenchyma. "The DDX3X expression level has been found to be positively associated with hypoxia-related proteins, including HIF1 alpha, in invasive breast cancer, suggesting a pro-metastatic role for DDX3X." (PMID 31906196, 2019). "DDX3X is relatively highly expressed in stomach adenocarcinoma, kidney clear cell carcinoma, breast invasive carcinoma, cervical and endocervical cancer, esophageal carcinoma, and head and a sub-population of neck squamous cell carcinomas." (PMID 31906196, 2019).
metastatic tumors (3 papers, 2017 to 2025). "That is, as there is a molecular dependency for DDX3X expression in cancer cells to maintain cellular and bioenergetic homeostasis, it is less likely to undergo marked changes during growth and establishment of metastatic tumors." (PMID 33196681, 2020).
neuroblastoma (3 papers, 2016 to 2025). Neuroblastoma (NB) is the most common solid, extracranial childhood tumor. "Affinity proteomics and molecular docking-based studies have revealed that ceftriaxone inhibits N-Myc translation by targeting DEAD-box helicase 3 X-linked (DDX3X), thereby inducing apoptosis in MYCN-amplified retinoblastoma and neuroblastoma cells." (PMID 41244073, 2025).
Neurodevelopmental delay (3 papers, 2020 to 2022). "Since this initial finding, more than 100 cases bearing pathogenic mutations in the DDX3X gene affected by variable degrees of neurodevelopmental delay have been identified, including several male patients." (PMID 32412080, 2020).
non-small cell lung carcinoma (3 papers, 2015 to 2019). A group of at least three distinct histological types of lung cancer, including non-small cell squamous cell carcinoma, adenocarcinoma, and large cell carcinoma. "Patients with low DDX3 expression were reported to have worse survival and higher relapse rates than those with high DDX3X expression in a non-small cell lung cancer cohort." (PMID 31906196, 2019).